TNF (tumor necrosis factor)
Diseases named in the same sentence as TNF in open-access papers (continued):
Sharing a sentence is not in itself a finding about the gene and the disease.
plaque psoriasis (continued). "In psoriasis vulgaris patient blood, NK cells were reported to have reduced cytotoxicity and production of proinflammatory cytokines TNF-α and IFN-γ." (PMID 33681365, 2021). "A study showed that patients with blood-heat syndrome of psoriasis vulgaris had substantially elevated levels of interferon-gamma, IL-17, IL-23, and TNF-α and significantly decreased levels of IL-4 and IL-10." (PMID 32843084, 2020). "Fifty patients with plaque psoriasis were selected from June 2017 to July 2018, divided into two groups, receiving methotrexate and tumor necrosis factor inhibitor." (PMID 32122693, 2020). "Tumor necrosis factor (TNF)-α was also intensely studied and the biological therapies targeting this cytokine revolutionized the treatment of psoriasis vulgaris." (PMID 30744173, 2019). "The first biologic to be approved for psoriasis vulgaris after the TNF-α inhibitors was ustekinumab, which is a monoclonal antibody directed against the p40 subunit." (PMID 30909615, 2019). "Conventional plaque psoriasis had a significantly higher percentage of IL-17A and TNF-α from CD8+ T cells relative to palmoplantar psoriasis (p = 0.044 and p = 0.044 respectively)." (PMID 30054515, 2018). "Adalimumab is a biological medicine, one of the three anti-TNF drugs used in the psoriasis vulgaris and psoriasis arthritis treatment." (PMID 29487864, 2018). "Detailed knowledge on classical plaque psoriasis, particularly by identifying the relevant role of the TNF/IL-23/TH17 axis in its pathogenesis, has allowed for novel, more targeted therapies." (PMID 30555460, 2018). "At present, biologics directed against the cytokines TNFα, IL-17, IL-22, and IL-12/23 have been approved for the treatment of moderate-severe plaque psoriasis by the FDA and EMA31." (PMID 29515113, 2018). "Adalimumab is a biological medicine, one of the three anti-TNF drugs used in the treatment of psoriasis vulgaris and psoriasis arthritis." (PMID 29487864, 2018). "Although most studies used small sample sizes, analysis of the pooled data showed an elevated MD of serum IFN-γ, IL-17, IL-23, and TNF-α in patients with psoriasis vulgaris of blood-heat syndrome, when compared to the control groups." (PMID 27274756, 2016). "Meta-analysis of the results for all markers, including IFN-γ, IL-4, IL-17, IL-23, IL-6, TNF-α, and IL-10, for subjects with psoriasis vulgaris of blood-heat syndrome revealed significant between-study heterogeneity (I2 > 75%) with random-effects modeling." (PMID 27274756, 2016). "The pooled analyses suggest that levels of IFN-γ, IL-17, IL-23, and TNF-α are significantly elevated and that levels of IL-4 and IL-10 are significantly decreased in sera of patients with psoriasis vulgaris of blood-heat syndrome." (PMID 27274756, 2016). "Paradoxically, TNF-α in serum increased after 12 weeks of Etanercept treatment and the increase was significantly higher in thick plaque psoriasis compared to thin plaque psoriasis (p = 0.04), reflecting more circulating TNF-α in thick plaque psoriasis." (PMID 26176783, 2015). "The cytokines from the psoriatic plaque spread into the circulation, which was represented by high serum levels of TNF-α downstream cytokines, IL-6 and IL-8, in thick plaque psoriasis." (PMID 26176783, 2015). "The main aim of this study was to assess the serum levels of TNF-α, IL-12/23p40, and IL-17 in patients with plaque psoriasis, compare them with healthy controls, and correlate them with the disease severity." (PMID 25759829, 2014). "The balance between TNFα, IL‐37 and IL‐17 expression may therefore be important in establishing plaque psoriasis inflammatory borders." (PMID 39157924, 2025). "Biosimilars of TNF blockers are also FDA-approved for the treatment of plaque psoriasis." (PMID 40109802, 2025). "In contrast to psoriasis vulgaris, PPP predominantly affects middle-aged women and is strongly associated with smoking and certain infections (e.g., tonsillitis and dental infections), and drugs (e.g., TNF-a inhibitors)." (PMID 40429269, 2025).
plaque psoriasis (continued). "Finally, some findings—such as the fluctuating efficacy of anti–TNF-α agents—differ from those typically reported in plaque psoriasis trials." (PMID 41235248, 2025). "However, TNF-α is a central cytokine in the initiation of plaque psoriasis and contributes to its chronic persistence." (PMID 41303905, 2025). "European guidelines for the systemic treatment of moderate-to-severe psoriasis vulgaris suggest considering anti-TNFα agents, ustekinumab, IL-17, and IL-23 inhibitors for patients with cancer, with individualized assessments considering patient preferences and remission durations." (PMID 38610706, 2024). "A recent 2021 non-systematic review compiled available information from 127 studies containing 1023 plaque psoriasis cases that received TNF-α, IL-12/23, IL-17, and IL-23 inhibitors, observing adverse event rates of 4.17%, 9.49%, 12.4%, and 7.37%, respectively." (PMID 39569269, 2024). "In such cases, switching to secukinumab, which has a distinct mechanism of action, could be a prudent choice to avoid potential plaque psoriasis flare-ups that may occur with a step-down in treatment to anti-TNFα agents." (PMID 39728081, 2024). "While anti-TNFα agents are also indicated for the treatment of hidradenitis suppurativa, many patients with concomitant plaque psoriasis, as in our study cohort, may have already received prior therapy with these biologics." (PMID 39728081, 2024). "The simple score, composed of CRP, IL-6 and TNF-α, with the cut-off value of 1.8, also showed satisfying predictive performance for PsA among the retrospective cohort of psoriasis vulgaris patients externally (AUC = 0.686, p = 0.010, sensitivity = 59.1%, specificity = 78.1%)." (PMID 39335643, 2024). "The recommended dose of secukinumab for patients with PsA and axSpA is 150 mg (300 mg in patients with PsA and concomitant moderate-to-severe plaque psoriasis or an inadequate response to a TNF-α inhibitor), with the possibility of increasing to 300 mg as needed." (PMID 37663578, 2023). "Hence, it should be considered as a possible useful clinical marker for anti-TNF-α treatment outcomes in patients with moderate-to-severe plaque psoriasis." (PMID 37239484, 2023). "There is currently a lack of real‐world clinical data regarding the safety and efficacy of coronavirus disease 2019 (COVID‐19) vaccines with respect to plaque psoriasis treatment involving tumor necrosis factor‐α (TNF‐α) and interleukin‐17A (IL‐17A) inhibitors." (PMID 37506146, 2023). "A central role in the pathogenesis of psoriasis vulgaris has been ascribed to the proinflammatory cytokines tumor necrosis factor (TNF)-alpha, interleukin (IL)-23, and IL-17, with upregulation of the Th1 and Th17 subsets and dysfunction of the regulatory T cells." (PMID 36615129, 2022). "Investigated TNF inhibitors (adalimumab and etanercept) and IL-17 and IL-12/23 inhibitors (ixekizumab, secukinumab, and ustekinumab) evaluated in pediatric plaque psoriasis achieve superior efficacy over control arms, measured by PASI75 and PASI90 after 3 months of treatment." (PMID 36226155, 2022). "TNF-α inhibitors are a class of biologics used to treat moderate to severe plaque psoriasis." (PMID 34884596, 2021). "Furthermore, IL-29 up-regulated the mRNA expression levels of IL-6, IL-17 and TNF-α in PBMCs from psoriasis vulgaris patients." (PMID 34030913, 2021). "TNF-α inhibitors are an important treatment option for moderate-to-severe plaque psoriasis." (PMID 33916122, 2021). "Pre-selected SNP sets were associated with psoriasis vulgaris analysis, which was used to identify four SNP-associated targeted therapy efficiencies: IL1β (rs1143633), IL4 (IL13) (rs20541), IL23R (rs2201841), and TNFα (rs1800629) genes." (PMID 33383665, 2020). "Blockers of TNF (TNFSF2) are already approved as anti-inflammatory agents for plaque psoriasis." (PMID 28530223, 2017).
plaque psoriasis (continued). "In addition, treatment with a TNFα inhibitor downregulated SRSF1 expression in peripheral blood mononuclear cells (PBMCs) from psoriasis vulgaris patients." (PMID 25658361, 2015). "Furthermore, while IL-36 signaling—strongly induced by TNF-α and IL-17—has been established as a driver of plaque psoriasis, its inhibition has been shown to reduce inflammation and Th17 cell activity, potentially contributing to the unique pustule formation observed in PPP." (PMID 40429269, 2025). "Considering apremilast’s role in reducing IL-17F, IL-17A, IL-22, and TNF-α plasma levels in patients with moderate to severe plaque psoriasis, it could be hypothesized that apremilast acts as a pleiotropic molecule, blocking a common pathway shared by both PsO and MetS." (PMID 39204094, 2024). "We performed a systematic review and meta-analysis to determine whether seven well-known immunological serum markers (IFN-γ, IL-4, IL-17, IL-23, IL-6, TNF-α, and IL-10) are elevated or decreased in patients with psoriasis vulgaris of blood-heat syndrome compared with controls." (PMID 27274756, 2016). "However, polymorphism in TNF (tumor necrosis factor) promoters 238 and 308 have been associated with psoriasis vulgaris but not with PPP." (PMID 27152848, 2016). "Biologics, such as tumor necrosis factor (TNF) inhibitors and interleukin (IL) inhibitors, have revolutionized the management of plaque psoriasis by providing a targeted therapeutic approach that addresses the underlying immunological dysfunction." (PMID 40282856, 2025). "Increased serum levels of TNF-α, IL-17, IL-22, and IFN-γ have been detected in patients with PPP in comparison to healthy subjects, suggesting a similar inflammatory pattern to psoriasis vulgaris." (PMID 34409425, 2021). "Patients with mild to moderate plaque psoriasis were treated with 5% HP extract and showed a significant reduction of the PASI and the lesional TNF-α expression." (PMID 33801280, 2021). "In both GPP and plaque psoriasis, defects in inflammatory mediators that are involved in allergic rhinoconjunctivitis, including pro‐inflammatory IL (specifically IL‐6) and TNF‐α,16, 17 also contribute to the manifestation of GPP and plaque psoriasis." (PMID 34390028, 2021). "Based on the study outcomes, we will assess the severity of the psoriasis vulgaris and serum VEGF, TNF-α, IL-17, and IL-23 levels." (PMID 32384509, 2020). "Drugs targeting TNFα, IL-23, and IL-17 and signaling pathways such as JAK/STAT are effective in the clinical management of plaque psoriasis." (PMID 30909615, 2019). "In classical plaque psoriasis, early transient overexpression of type-I IFN is replaced by a dominant TNF-driven chronic inflammation." (PMID 30555460, 2018). "In summary, patients with psoriasis vulgaris of blood-heat syndrome show significantly elevated levels of IFN-γ, IL-17, IL-23, and TNF-α and decreased levels of IL-4 and IL-10." (PMID 27274756, 2016). "Serum levels of the inflammatory mediators IL-6, IL-8, IL-12, IL-18, TNF-α and INF-γ were found to be elevated in plaque psoriasis." (PMID 24651659, 2014). "TNF-α and EGFR ligands are overexpressed in plaque psoriasis compared with uninvolved skin or healthy control skin." (PMID 25384035, 2014). "Psoriasis vulgaris is an inflammatory skin disease mediated by Th1 and Th17 cytokines with relevant contributions of IFN-γ, TNF-α, and IL-17." (PMID 24587313, 2014). "Herein, we report data from a retrospective case series of patients with plaque psoriasis treated with intravenous infliximab (IV-IFX; Anti TNF-α) and transitioned to subcutaneous infliximab (SC-IFX) to compare clinical and patient-reported outcomes across routes." (PMID 41464777, 2025). "In the retrospective cohort, the previous results of serum CRP, IL-6, and TNF-α detection were collected for the included psoriasis vulgaris patients who did not progress into PsA, and the clinical prognosis was followed up for at least 4 years." (PMID 39335643, 2024).
plaque psoriasis (continued). "IL-17 inhibitors may have a faster time to meaningful plaque psoriasis improvement due to the target IL-17 cytokine being more downstream in the pathway than IL-23 or TNF-α (targets of IL-23 and TNF-α inhibitors)." (PMID 39274352, 2024). "The drug became the first small molecule TNF inhibitor to enter clinical trials with the ongoing recruitment for phase 2 trials in an estimated 240 patients with RA (NCT06073093) and in an estimated 207 patients with plaque psoriasis (NCT06073119)." (PMID 39297883, 2024). "Here we describe a protocol to evaluate the efficacy and safety of various bathwater temperatures and herbal concentrations on psoriasis vulgaris, and their effect on serum vascular endothelial growth factor (VEGF), tumor necrosis factor α (TNF-α), interleukin 23 (IL-23), and interleukin 17 (IL-17)." (PMID 32384509, 2020). "Unlike the other cases, our patient’s plaque psoriasis flared while on anti-TNF requiring a transition onto anti-IL 12/23 therapy which is currently maintaining both his CD and plaque psoriasis." (PMID 31488067, 2019). "In vitro and in vivo animal experiments show that the EPS/CPT emulsion can effectively treat psoriasis vulgaris by increasing the accumulation of CPT in psoriatic skin lesions and reducing the levels of inflammatory cells and inflammatory factors (TNF and IL6)." (PMID 31861934, 2019). "Therefore, cytokines such as IL-17A, IL-22, IL-23, and TNF-α were found to be elevated in both psoriasis vulgaris and GPP; however, GPP lesions yielded significantly higher IL-1 and IL-36, and lower IL-17A and interferon-gamma (IFN-γ) messenger RNA (mRNA) expressions, than plaque psoriasis lesions." (PMID 34445754, 2021). "We conducted a cross-sectional study to compare the levels of serum inflammatory indicators between psoriasis vulgaris patients who progressed to PsA and those who did not, and found that CRP, IL6 and TNF-α levels were all higher in PsA patients than in controls." (PMID 39335643, 2024). "As for the technological restriction, only a few psoriasis vulgaris patients showed serum CRP, IL-6 and TNF-α detected previously, so most patients could not be included in this retrospective cohort." (PMID 39335643, 2024).
vasculitis (127 papers, 2005 to 2025). "Molecular mimicry has been implicated in the pathogenesis of drug-induced vasculitis; however, further research is needed to understand its role in TNF inhibitor-induced reactions fully." (PMID 41158918, 2025). "Certolizumab pegol (such as Cimzia), a commonly used TNF inhibitor, has been associated with rare dermatologic reactions, including drug-induced vasculitis, which are mostly categorized as small-vessel vasculitis." (PMID 41158918, 2025). "TNF-α acts as a potent activator of ECs, and activated ECs have been associated with vascular EC injury in the development of vasculitis, thrombosis, and other vascular diseases." (PMID 38675220, 2024). "Given the genetic nature of the disease TNF inhibitors should be continued for life because of the risk of relapse after therapy discontinuation, especially in those with vasculitis and CNS manifestations." (PMID 38357265, 2023). "Recently, we have demonstrated that Adeno-associated virus (AAV)–mediated expression of human TNF-α in the murine eye induces retinal inflammation including vasculitis and fibrosis, thereby mimicking human disease-relevant pathologies." (PMID 35579886, 2022). "Vasculitis causes tissue injury and releases cytokines like IL-6, IL-1β, and TNFα, which in turn trigger endothelial exocytosis and so on." (PMID 35061142, 2022). "In Bechet’s disease, another vasculitis involving large vessels in vast majority of them, γδ T cells are shown to secrete TNF-α and CXCL8 causing activation signal and recruitment of neutrophils and monocytes to sites of infection and inflammation." (PMID 35813204, 2022). "Once generated, PR3-ANCA binds to partially activated neutrophils primed e.g. by TNF alpha (TNFα) and causes their excessive auto-immune activation responsible for vasculitis lesions." (PMID 33679731, 2021). "TNF-α induced elastin degradation is associated with vasculitis caused by Kawasaki disease and vascular aneurysms, and the TNF-α deficiency prevents elastin degradation and aneurysm formation." (PMID 34917605, 2021). "Several studies have stated that TNF-α participates in the pathogenesis of scleritis, but also in several systemic autoimmune diseases and vasculitis, of which some are associated with scleritis." (PMID 33287909, 2020). "Proteinase 3-ANCA have a central role in GPA pathophysiology: they bind neutrophils previously primed by tumor necrosis factor alpha (TNFα; called primed-neutrophils) and cause their auto-immune activation, which is responsible for vasculitis lesions." (PMID 33101296, 2020). "Because of the limited data, we cannot know how different anti-TNF-α agents cause vasculitis or how to change anti-TNF-α treatment in a patient with vasculitis." (PMID 25133007, 2014). "Anti-TNF-associated vasculitis pathogenesis may involve antibody formation against anti-TNF molecules or cytokine ratio disturbances." (PMID 39861147, 2025). "The mechanism underlying TNF inhibitor-induced vasculitis remains incompletely understood." (PMID 40385904, 2025). "In a retrospective review of the patients evaluated at the Mayo Clinic from January 1998 to March 2011, only eight patients with vasculitis associated with anti-TNF therapy were identified, and, of these, only four had IBD." (PMID 37176606, 2023). "For example, abatacept in CTLA4 haploinsufficiency, LRBA and DEF6 deficiencies; tocilizumab in STAT3 GOF; JAK inhibitors in STAT3 and STAT1 GOF patients; alemtuzumab for CD25 deficiency; PIK3δ inhibitors for APDS or anti-TNFα therapy for vasculitis in ADA2 deficiency." (PMID 34447369, 2021). "Inhibitors of tumor necrosis factor (TNF) are an effective therapy for rheumatic and systemic autoimmune diseases but the increasing use of these agents has caused secondary autoimmune conditions, such as vasculitis." (PMID 25544845, 2014).